TNF (tumor necrosis factor)
Diseases named in the same sentence as TNF in open-access papers (continued):
Sharing a sentence is not in itself a finding about the gene and the disease.
vitamin D deficiency (continued). "The results showed that the levels of TNF-alpha, IL-1 beta, IL-6, and hs-CRP were not connected with vitamin D deficiency." (PMID 32371900, 2020). "The inflammation markers, including interleukin (IL)−1 beta, IL-6, tumor necrosis factor (TNF)-alpha, and, high-sensitivity C-reactive protein (hs-CRP) were also not significantly different between the study patients with and without vitamin D deficiency." (PMID 32371900, 2020). "As observed previously with higher doses of OVA/Alum, vitamin D deficiency enhanced the capacity of ADLN cells to proliferate and secrete cytokines like IL-4, IL-5, IL-10 (data not shown), but not IL-6, IL-17, TNF or IFNγ (data not shown)." (PMID 23826346, 2013). "Furthermore, an important finding in this study, compared to other up‐to‐date research, is that vitamin D deficiency was strongly associated with the presence of albuminuria in T2D patients, independent of basic inflammatory markers (hs‐CRP and TNF‐α) and the GFR." (PMID 40804707, 2025).
gastritis (107 papers, 2008 to 2026). Inflammation of the stomach. "In the early stage of H. pylori-induced gastritis or gastritis caused by other stimuli, immune cells such as macrophages and Th1 cells release large amounts of pro-inflammatory factors, including TNF-α, IL-1β, and IFN-γ." (PMID 41376630, 2025). "The study provided evidence of Hp, gastric epithelial cells, IL-33, MCs, and TNF-α forming a complex regulatory network that, when disrupted, contributes to Hp infection-associated gastritis." (PMID 39728753, 2024). "Several studies indicate that increased expression of TNF-α or TNF-α polymorphisms has been associated with an augmented susceptibility to chronic atrophic gastritis, metastasis, tumorigenesis, and GC in patients." (PMID 39057074, 2024). "Gastric IL-33 resulted in increased TNF-α production from MCs in vitro, and in vivo and inhibited gastric epithelial cell proliferation, thus further promoting Hp-associated gastritis and bacteria proliferation." (PMID 39728753, 2024). "Our investigation delves into the differential expression of key cytokines in gastric tissue, including IL-1β, IL-6, IL-8, IL-12, IL-18, and TNF-α in the context of H. pylori-associated and H. pylori-independent gastritis." (PMID 38561502, 2024). "IL-1β, IL-6, and IL-8 were lower in H. pylori infection-associated gastritis samples, whereas the levels of IL-12, IL-18, and TNF-α were higher." (PMID 38561502, 2024). "In gastric diseases, TNF-α-308 G/A is associated with a high risk of chronic atrophic gastritis, intestinal metaplasia and GC." (PMID 32592356, 2020). "Increased TNF-α inhibited gastric epithelial cell proliferation, conducing to the progress of H. pylori-associated gastritis and bacteria colonization." (PMID 29691371, 2018). "Polymorphisms in the promoter of the gene encoding the tumor necrosis factor (TNFα-308) and interleukin 10 (IL-10) (IL-10-592 and -1082) also have an important role in the development of gastritis associated by H. pylori infection." (PMID 28512631, 2017). "We also observed that, in patients with chronic gastritis, TNF-α mRNA was overexpressed in relation to the control patients, and the association was greater among patients who had gastritis and were also H. pylori positive." (PMID 26719751, 2015). "The high levels of cytokines release, like TNF-a (Tumor necrosis factor-a), IL-6 (interleukin-6), and IL-10 (interleukin-10) caused by aspirin ingestion are critical in the acute phase of inflammation and severity of gastritis." (PMID 37184667, 2023). "Furthermore, some cytokines that induce G cells to secrete gastrin, such as ammonia and tumor necrosis factor-alpha, are released in H. pylori-associated gastritis, which further upregulates the gastrin levels." (PMID 35126509, 2022). "Especially, TNF which can be induced by Campylobacter concisus is associated with bitter taste, which is an important Damp Heat phenotype related to gastritis in traditional Chinese medicine." (PMID 30478535, 2019). "For example, increased production of pro-inflammatory cytokines in the mucus (such as IL-1, IL-6, IL-10, TNF-α, and interferon-γ) of those who are at risk of H. pylori infection is associated with gastritis induced by H. pylori and the severity of inflammation." (PMID 30320011, 2018). "In addition, we demonstrated a striking association between SNP −238 in TNF-α gene with gastritis and adenocarcinoma." (PMID 26504356, 2015). "This study demonstrates that SA-derived extracellular vesicles (SA-EVs) accumulate in gastric tissue, enter epithelial cells, and induce acute gastritis characterized by neutrophil infiltration and elevated cytokines (TNF-α, IL-6, IL-17A)." (PMID 41614638, 2026). "The EAA treatment markedly reduced acute gastritis symptoms and prevented inflammatory responses by suppressing TNF-α secretion and nitrite overproduction." (PMID 41423315, 2025).
gastritis (continued). "The analysis suggests that CXCL1 promotes the progression of HPI gastritis by regulating signaling pathways such as the TNF, NF-κB, and chemokine signaling pathway." (PMID 40825934, 2025). "TNF drives inflammation in H. pylori -induced gastritis by activating the NF-κB pathway, stimulating the release of other inflammatory cytokines." (PMID 41376630, 2025). "Interleukins 6 and 13 (IL-6 and IL-13) promote EBV proliferation, and elevated levels of pro-inflammatory cytokines such as IL-1β, tumor necrosis factor α (TNF-α), and IL-8 have been observed in EBV and H. pylori coinfection associated with severe gastritis." (PMID 40110195, 2025). "Our study provides invaluable insights into the inflammatory mechanisms involved by exploring key cytokines such as IL-1β, IL-6, IL-8, IL-12, IL-18, and TNF-α in gastritis." (PMID 38561502, 2024). "These investigators observed over-expression of ICAM-1 and TNF-α genes at the early stages of IND-induced gastritis." (PMID 38652367, 2024). "Commercially available ELISA plates were used to confirm further the influence of H. pylori infection on the expression of cytokines (IL-1β, IL-6, IL-8, IL-12, IL-18, and TNF-α) in gastritis." (PMID 38561502, 2024). "In our experimental study, we observed an increase in TNF-α levels in gastritis compared to normal, with notably higher levels in H. pylori-associated gastritis than in H. pylori-independent gastritis." (PMID 38561502, 2024). "Generally, cytokine levels were higher in gastritis, but in H. pylori-infected gastritis, IL-1β, IL-6, and IL-8 levels were lower compared to H. pylori-independent gastritis, while IL-12, IL-18, and TNF-α levels were higher." (PMID 38561502, 2024). "Studies have shown that TCM can reduce H. pylori-induced gastritis by decreasing the expression of IL-8, TNF-α, IL-6, iNOS, and IFN-γ." (PMID 38195483, 2024). "In parallel to infection with H. pylori, we also examined the response to TNF, a prototypical cytokine characterizing virtually all inflammatory conditions, including H. pylori-induced gastritis." (PMID 37894827, 2023). "For instance, neutrophils stimulate an inflammatory TNF-α/HDGF/COX-2 signaling cascade that plays an important role during Helicobacter pylori-induced gastritis and gastric carcinogenesis." (PMID 37827291, 2023). "TNF-α mRNA expression in the infected patients with PUD was significantly higher than in the patients with gastritis." (PMID 36057049, 2022). "TNF-α fold change in H. pylori-positive patients with PUD compared to H. pylori-positive patients with gastritis was 2.13-fold." (PMID 36057049, 2022). "In summary, in this study, Mb-ME reduced the production of nitric oxide; decreased the mRNA expression of pro-inflammatory genes such as TNF-α, IL-6, and iNOS; and relieved acute gastritis symptoms triggered by HCl/EtOH treatment." (PMID 35270116, 2022). "Based on the network pharmacological results, Rhizoma phragmitis and Rhizoma curcumae will modulate MAPK, TNF signaling circuits, and inflammatory factor target genes in the chronic atrophic gastritis rat model." (PMID 36003993, 2022). "Meaningful expression of TNF-α mRNA increased at H. pylori-positive patients with PUD than H. pylori-positive patients with gastritis." (PMID 36057049, 2022). "In rats with gastritis, high beta-glucan consumption resulted in a significant reduction in the concentration of TNF-alpha in the stomach tissue, while in humans, the concentration of this immune parameter in the blood did not change." (PMID 34444949, 2021). "Our results indicate that heparanase promotes M1 polarization of macrophages driven by H. pylori or LPS + INF-γ, resulting in increased expression of pro-inflammatory cytokines such as IL-1β, IL-6 and TNF-α, and further aggravating the severity of gastritis." (PMID 34220822, 2021). "Similar to the in vitro results, iNOS and TNF-α mRNA levels in the stomach tissue lysates of gastritis mice were also lower in the alverine administration group." (PMID 32326535, 2020).
gastritis (continued). "In turn, TNF-α aggravates the inflammation and H. pylori colonization; furthermore, IL-33 inhibits gastric epithelial cell renewal and promotes gastritis progress." (PMID 29691371, 2018). "Secreted by monocytes and macrophages, TNF-α stimulates the production of a series of cytokine and play an important part in gastritis." (PMID 30382864, 2018). "These strains induced interleukin- (IL-) 8 and tumor necrosis factor (TNF) expression and stimulated macrophages against ethanol-induced gastritis and liver injury in mice." (PMID 29998137, 2018). "And then, IL-33 enhances mast cell-derived tumor necrosis factor-alpha (TNF-α) secretion in gastritis." (PMID 29691371, 2018). "The serum TNF-α level was also significantly elevated in H.pylori-induced gastritis in rats, which resulted in significant deterioration in stomach pathology, and added apoptotic epithelial cells." (PMID 29691371, 2018). "In conclusion, the significant elevation of IL-17 and IL-23 and high expression of IL-21 and TNF-α in the serum of H. pylori-positive patients further supports the role of Th-17 cells in the pathogenesis of H. pylori infection and the severity of gastritis." (PMID 29391865, 2017). "In the second analysis, the gastritis group was divided according to the presence of H. pylori: TNF-α expression was significantly higher in patients with gastritis who had tested positive for H. pylori (p = 0.0001; RQ = 3.774)." (PMID 26719751, 2015). "Recent studies tend to suggest that the immunosuppressive and pro-inflammatory microenvironment created by chronic atrophic gastritis, characterized by the continuous high expression of cytokines such as IL-6 and TNF-α, may be a more upstream driving factor." (PMID 41333217, 2025). "Artemisia capillaris Thunb. from Asteraceae revealed remarkable early-stage anti-gastritis ability and anti-chronic gastritis and anti-precancerous lesion capacity by down-regulating IL-1β, IL-6, TNF-α, COX-2, PGE2, gastric F4/80 protein, and MDA with low p-p65 and pSTAT3 expression." (PMID 40264171, 2025). "Consequently, TNF-α has been identified as a principal mediator in ethanol-induced gastritis pathogenesis, with TNF-α’s expression levels serving as a reliable indicator for quantifying inflammatory progression in gastric mucosa." (PMID 40361682, 2025). "Furthermore, individuals with Hp gastritis at high altitudes demonstrate elevated levels of serum TNF-α, IL-1β, IL-6, and MDA, as well as reduced serum SOD and GSH-Px activities." (PMID 38970131, 2024). "EPS54 also significantly alleviated the symptoms of gastritis in the H. pylori-infected mice by down-regulating the mRNA expression levels of pro-inflammatory cytokines IL-6, IL-8, IL-1β and TNF-α and up-regulating the mRNA expression of inflammatory cytokines IL-10 in gastric cells." (PMID 38978704, 2024). "Furthermore, CagA provokes chronic atrophic gastritis by inducing inflammatory cytokines, such as interleukin (IL)-1, IL-6, IL-8, IL-18, and tumor necrosis factor α (TNFα)." (PMID 37629426, 2023). "The activation of NF-κ B may in turn aggravate gastritis via the induction of proinflammatory cytokines such IL-1, IL-6, IL-8 and TNF-α." (PMID 36841844, 2023). "It is well established that in gastritis and peptic ulcer, a massive infiltration of activated neutrophils is evident, as well as an upregulation of pro-inflammatory cytokines release such as TNF-α and IL-1." (PMID 36979808, 2023). "Expression of TNF-α was significantly increased in the PUD group than the gastritis group." (PMID 36057049, 2022). "The increased TNF-α mRNA expression may be able to reflect the degree of tissue damage affected by a peptic ulcer in comparison to gastritis patients." (PMID 36057049, 2022). "Additionally, PDG derived from a marine sponge-associated actinomycete decreased the levels and expression of various inflammatory markers, including myeloperoxidase, IL-1β, TNF-α, iNOS, Cox-2, and NF-κB in a murine gastritis model." (PMID 35336729, 2022).
gastritis (continued). "To investigate whether naringenin could affect ethanol-induced gastritis, we examined the effects on the secretion of TNF-α, IL-6, and IL-8 expression in ethanol-stimulated KATO III cells." (PMID 34769415, 2021). "The possible inflammatory markers that can be used to evaluate gastritis are the interleukin family—mainly IL-6—and other proinflammatory cytokines, namely the tumor necrosis factor alpha (TNF-α), IL-1, and IL-8, C-reactive protein (CRP), platelets and neutrophils." (PMID 32722268, 2020). "Interestingly, EtOH/HCl-induced gastritis mouse models demonstrated an increase in IL-1β, iNOS, TNF-α, INF-β, and COX-2 gene expression and an increase in phosphorylation of p65, Syk, and JAK2." (PMID 31929819, 2019). "Moreover, the upregulated IL-33 induced mast cells to secrete TNF-α, which inhibited gastric epithelial cell renewal and aggravated gastritis." (PMID 29691371, 2018). "This led us to hypothesize that, during H. pylori infection, IL-33 might exert proinflammatory effects and promote TNF-α production and, as a result, lead to gastritis." (PMID 29691371, 2018). "Our findings provide insights into how IL-33, mast cells, TNF-α, and gastric epithelial cells may interact in H. pylori-induced gastritis." (PMID 29691371, 2018). "Similarly, feeding an A2AAR agonist to IL-10 deficient mice suffering from gastritis due to H. pylori attenuated gastritis and lowered TNF-α and IFN-γ in the gastric mucosa, but led to increased bacterial colonization." (PMID 25950510, 2015). "EPS54 could also effectively alleviate the gastritis in the H. pylori-infected mice by down-regulating the mRNA expression levels of pro-inflammatory cytokines IL-6, IL-8, IL-1β and TNF-α and up-regulating the mRNA expression of inflammatory cytokine IL-10 in gastric cells." (PMID 38978704, 2024). "Moreover, it was found that silencing of AQP5 could restrain levels of inflammatory factor (TNF-α and IL-1β) and apoptosis of GECs in mice with H. pylori-related gastritis." (PMID 35538066, 2022). "ROS is crucial in the development of gastritis and GU, acting as a hub that integrates signals from various upstream receptors, such as RAGE, TNF, and TLRs." (PMID 40606619, 2025). "Neutral corn protein hydrolysate attenuated gastritis through reduction of MPO, IL-1β, IL-6, KC, TNF-α, and MCP-1." (PMID 40264171, 2025). "The amounts of IL-2, IL-4, IL-17A, IL-17F, IL-22, TNF-α, and TFN-γ were significantly different in patients with gastritis compared with Hp- subjects." (PMID 39807418, 2024). "Accordingly, IL-2, IL-17-A, IL-17F, IL-22, TNF-α, and IFN-γ showed significant increases in patients with mild and moderate gastritis compared with the Hp- subjects." (PMID 39807418, 2024). "The levels of IL-2, IL-17A, IL-17F, IL-22, TNF-α, and IFN-γ were significantly higher in patients with mild and moderate gastritis than Hp- group (P≤0.05)." (PMID 39807418, 2024). "We also confirmed that Mh-ME mitigates acute gastritis derived from HCl/EtOH in ICR mice, ameliorating the expression of IL-1β and tumor necrosis factor-alpha (TNF-α)." (PMID 37687291, 2023). "Even in in vivo models of Helicobacter pylori-induced gastritis in Mongolian gerbils, CAPE can prevent NF-κβ activation and decrease COX-2, iNOS, IL-1β, and TNF-α mRNA expression." (PMID 36673507, 2023). "For instance, H. pylori–induced gastritis patients showed higher expressions of TLR2, TLR4, and TNF–α in their gastric biopsies of while metaplasia and dysplasia patient samples exhibited higher TLR2 expression." (PMID 36317079, 2022). "Experiments in the gastritis mouse model indicated that Pp-EE suppresses HCl/EtOH-induced gastric lesions, the expression levels of COX-2, IL-6, and TNF-α, and the phosphorylation of p65, p50, and Src." (PMID 35807703, 2022).